GSDMD (gasdermin D)
Description:
[Gasdermin-D]: Precursor of a pore-forming protein that plays a key role in host defense against pathogen infection and danger signals. This form constitutes the precursor of the pore-forming protein: upon cleavage, the released N-terminal moiety (Gasdermin-D, N-terminal) binds to membranes and forms pores, triggering pyroptosis. [Gasdermin-D, N-terminal]: Promotes pyroptosis in response to microbial infection and danger signals. Produced by the cleavage of gasdermin-D by inflammatory caspases CASP1, CASP4 or CASP5 in response to canonical, as well as non-canonical (such as cytosolic LPS) inflammasome activators. After cleavage, moves to the plasma membrane where it strongly binds to inner leaflet lipids, including monophosphorylated phosphatidylinositols, such as phosphatidylinositol 4-phosphate, bisphosphorylated phosphatidylinositols, such as phosphatidylinositol (4,5)-bisphosphate, as well as phosphatidylinositol (3,4,5)-bisphosphate, and more weakly to phosphatidic acid and phosphatidylserine. Homooligomerizes within the membrane and forms pores of 10-15 nanometers (nm) of inner diameter, allowing the release of mature interleukin-1 (IL1B and IL18) and triggering pyroptosis. Gasdermin pores also allow the release of mature caspase-7 (CASP7) (By similarity). In some, but not all, cells types, pyroptosis is followed by pyroptotic cell death, which is caused by downstream activation of ninjurin-1 (NINJ1), which mediates membrane rupture (cytolysis). Also forms pores in the mitochondrial membrane, resulting in release of mitochondrial DNA (mtDNA) into the cytosol (By similarity). Gasdermin-D, N-terminal released from pyroptotic cells into the extracellular milieu rapidly binds to and kills both Gram-negative and Gram-positive bacteria, without harming neighboring mammalian cells, as it does not disrupt the plasma membrane from the outside due to lipid-binding specificity. Under cell culture conditions, also active against intracellular bacteria, such as Listeria monocytogenes (By similarity). Also active in response to MAP3K7/TAK1 inactivation by Yersinia toxin YopJ, which triggers cleavage by CASP8 and subsequent activation (By similarity). Required for mucosal tissue defense against enteric pathogens (By similarity). Activation of the non-canonical inflammasome in brain endothelial cells can lead to excessive pyroptosis, leading to blood-brain barrier breakdown (By similarity). Strongly binds to bacterial and mitochondrial lipids, including cardiolipin. Does not bind to unphosphorylated phosphatidylinositol, phosphatidylethanolamine nor phosphatidylcholine. [Gasdermin-D, p13]: Transcription coactivator produced by the cleavage by CASP3 or CASP7 in the upper small intestine in response to dietary antigens (By similarity). Required to maintain food tolerance in small intestine: translocates to the nucleus and acts as a coactivator for STAT1 to induce the transcription of CIITA and MHC class II molecules, which in turn induce type 1 regulatory T (Tr1) cells in upper small intestine (By similarity). [Gasdermin-D, p40]: Produced by the cleavage by papain allergen. After cleavage, moves to the plasma membrane and homooligomerizes within the membrane and forms pores of 10-15 nanometers (nm) of inner diameter, allowing the specific release of mature interleukin-33 (IL33), promoting type 2 inflammatory immune response.
Synonyms: DFNA5L; GSDMDC1; FKSG10; FLJ12150; DF5L
Tractability: Small molecule: a high-quality ligand is known. Antibody: UniProt places it where antibodies can reach, with high confidence; its Gene Ontology location is reachable by antibodies, with high confidence; UniProt predicts a signal peptide or a membrane-spanning region. PROTAC: UniProt records ubiquitination sites on it; ubiquitination databases record sites on it; its protein half-life has been measured; a small molecule that binds it is known.
Gene: Protein-coding gene on chromosome 8 (143,553,207 to 143,563,062, forward strand). Ensembl gene ENSG00000104518.
Subcellular location: Cytoplasm, cytosol (Gasdermin-D); Inflammasome; Cell membrane (Gasdermin-D, N-terminal); Secreted; Mitochondrion membrane; Cytoplasm, cytosol (Gasdermin-D, N-terminal); Nucleus (Gasdermin-D, p13); Cytoplasm, cytosol (Gasdermin-D, C-terminal)
Subcellular location (Human Protein Atlas): Nucleoplasm
Pathways (Reactome):
Immune System: CASP4-mediated substrate cleavage; CASP5-mediated substrate cleavage; Interleukin-1 processing; Neutrophil degranulation; Regulation of TLR by endogenous ligand
Programmed Cell Death: Pyroptosis; Release of apoptotic factors from the mitochondria
Disease: Purinergic signaling in leishmaniasis infection
Gene Ontology:
Molecular function: protein binding; cardiolipin binding; phosphatidic acid binding; phosphatidylinositol-4,5-bisphosphate binding; phosphatidylinositol-4-phosphate binding; phosphatidylserine binding; wide pore channel activity
Biological process: defense response to bacterium; defense response to Gram-negative bacterium; defense response to Gram-positive bacterium; pore complex assembly; positive regulation of interleukin-1 beta production; protein homooligomerization; pyroptotic inflammatory response; positive regulation of inflammatory response; protein secretion; pyroptotic cell death; transmembrane transport
Cellular component: nucleoplasm; plasma membrane; canonical inflammasome complex; cytosol; extracellular region; ficolin-1-rich granule lumen; mitochondrial membrane; NLRP3 inflammasome complex; nucleus; specific granule lumen; tertiary granule lumen
Genetic constraint (gnomAD): Loss-of-function variants: 46 observed, 39.39 expected, observed/expected ratio (o/e) 1.17, 90% interval 0.92 to 1.49. The upper end of that interval is the gene's LOEUF score, 1.49, which puts it in group 6 of 6, group 1 being the genes least tolerant of losing a copy. Missense variants: 649 observed, 606.22 expected, observed/expected ratio (o/e) 1.07, 90% interval 1 to 1.14. Synonymous variants: 307 observed, 261.73 expected, observed/expected ratio (o/e) 1.17, 90% interval 1.07 to 1.29.
Homologues: Orthologues: chimpanzee GSDMD (98% identical), macaque GSDMD (88% identical), pig GSDMD (65% identical), guinea pig GSDMD (61% identical), dog GSDMD (60% identical), rabbit GSDMD (60% identical), mouse Gsdmd (57% identical), rat Gsdmd (55% identical), zebrafish pjvk (14% identical). Paralogues in human: GSDMA (31% identical), GSDMC (29% identical), GSDMB (23% identical), PJVK (14% identical).
Diseases named in the same sentence as GSDMD in open-access papers:
GSDMD is named in the same sentence as 399 diseases in open-access papers, as found by Europe PMC text mining. Sharing a sentence is not in itself a finding about the gene and the disease. The quoted sentences say what the papers report.
Sepsis (186 papers, 2016 to 2026). Sepsis is defined as life-threatening organ dysfunction caused by a dysregulated host response to infection. "Sepsis, a systemic inflammatory response syndrome caused by infection, is closely associated with pyroptosis mediated by the caspase-GSDMD pathway." (PMID 39994107, 2025). "A recent study provides direct genetic evidence for this, demonstrating that GSDMD knockout alleviates sepsis-associated skeletal muscle atrophy in mice." (PMID 41334559, 2025). "Pyroptosis is intricately associated with organ dysfunction induced by sepsis, and current strategies aimed at modulating pyroptosis primarily focus on targeting inflammasomes, key caspase enzymes, GSDMD proteins, and downstream inflammatory mediators." (PMID 40708650, 2025). "This study investigated the association between GSDMD-NETs axis activation and sepsis-induced coagulopathy (SIC), as well as the potential association with glycocalyx damage." (PMID 40766307, 2025). "Recent studies have shown the key role of NLRP3/caspase-1/GSDMD-dependent pyroptosis signaling pathway in the regulation of sepsis-associated organ dysfunction." (PMID 40708650, 2025). "Consistent with our findings in LPS shock, hepatocyte GSDMD-mediated HMGB1 contributed to endothelial GSDMD-mediated systemic vascular damage in sepsis, and endothelial Gsdmd deficiency prevented sepsis-induced lethality." (PMID 39927458, 2025). "The lung wet‐to‐dry weight ratio also showed that the wet/dry weight ratios of GSDMDhep‐/− mice were significantly higher than those of GSDMDflox+/+ mice, indicating that hepatic GSDMD deficient mice were more susceptible to sepsis." (PMID 40856013, 2025). "This study unveils the crucial contribution of Casp11 and GSDMD to cognitive impairments and spatial memory loss in a murine sepsis model." (PMID 39179968, 2024). "The NLRP3/Caspase/GSDMD signaling pathway of sepsis‐induced ALI in mice caused by pyroptosis was assessed by real‐time quantitative PCR, enzyme‐linked immunoadsorption assay, western blot analysis, PI staining, and flow cytometry." (PMID 38501547, 2024). "Previous studies, including our own research, have indicated that gasdermin-D(GSDMD)-mediated endothelial cells pyroptosis contributes to sepsis-associated endothelial injury." (PMID 37962578, 2024). "This study unveils a significant contribution of Casp11 and GSDMD to cognitive impairments and spatial memory loss in a murine sepsis model." (PMID 39179968, 2024). "The study identified seven important PRGs including CHMP7, NLRC4, PLCG1, IRF1, CASP4, NLRP1, GSDMD associated with sepsis." (PMID 37939116, 2023). "GSDMD has been linked to accelerating sepsis by providing a conduit for passive release of both SQSTM1, a regulator of innate immunity, and F3, a blood coagulation initiator downstream of LPS or STING activation, respectively." (PMID 37266429, 2023). "In patients with sepsis, over-expressed caspase-1 or caspase-4/5 combined with lipopolysaccharide (LPS) recognizes and activates gasdermin-D (GSDMD), an actor of pyroptosis, which can cause immune cell death." (PMID 37292207, 2023). "Numerous studies have shown that the factors involved in the NLPR3/Caspase-1/GSDMD process, a classical pathway associated with pyroptosis, are highly expressed in patients and animals with sepsis." (PMID 37939116, 2023). "Numerous studies have shown that cell pyroptosis, a programmed cell death dependent on GSDMD activation, is closely related to the systemic inflammatory response and intestinal barrier dysfunction caused by sepsis." (PMID 36589684, 2022). "In sepsis, active eCIRP secretion is shown to be linked to inflammasome activation, regulated by the gasdermin D (GSDMD) pathway." (PMID 35967397, 2022). "Evidence also demonstrates that GSDMD-mediated pyroptosis is involved in sepsis-associated acute kidney injury (AKI) and lung injury." (PMID 34820388, 2021).
Sepsis (continued). "Disulfiram, as previously explained, acts by blocking gasdermin D pore formation and shows a reduction in inflammatory cytokines level in a mouse model of sepsis associated with a longer survival rate." (PMID 34831246, 2021). "Pyroptosis of gasdermin D (GSDMD)-mediated tubular epithelial cells (TECs) play important roles in pathogenesis of sepsis-associated AKI." (PMID 34012408, 2021). "Similarly, puerarin protected against sepsis-associated encephalopathy by inhibiting NLRP3/Caspase-1/GSDMD pyroptosis pathway and reducing blood-brain barrier damage." (PMID 40708650, 2025). "Sepsis-induced nuclear autophagy might be linked to mitochondrial damage through GSDMD, providing a potential mechanistic insight into the pathology of SAE." (PMID 38627764, 2024). "Furthermore, it was observed that mice deficient in GSDMD exhibit an increased rate of survival following the induction of sepsis." (PMID 39267971, 2024). "Consequently, interventions targeting the functionality of GSDMD offer a potential opportunity for the prevention and treatment of sepsis‐associated DIC, rendering it an important therapeutic target for pharmacological intervention in the management of sepsis." (PMID 39445002, 2024). "In addition, GSDMD deficiency further inhibits DIC in sepsis in the liver microvasculature and protects against obesity-induced HCC38,40." (PMID 36967609, 2023). "Downregulated GSDMD alleviated Candida albicans-associated sepsis." (PMID 38022612, 2023). "Consistently, GSDMD deficiency protected mice from the lethality in LPS-induced sepsis." (PMID 35774778, 2022). "Gasdermin-D (GSDMD)-mediated pyroptosis is an important innate immune response to antagonize pathogen infection, but excessive response can cause a series of diseases including sepsis." (PMID 34922574, 2021). "Therefore, in the present study, we investigated the effect of GSDMD in LPS-induced cardiac dysfunction and the underlying mechanisms, aiming to find a feasible target for the treatment of sepsis-induced myocardial dysfunction." (PMID 34820388, 2021). "In addition, knockout of the gene encoding the pyroptotic protein Gasdermin D (GSDMD) and overexpression of autophagy-related proteins can effectively inhibit pyroptosis and prolong the survival of a sepsis animal model." (PMID 32851082, 2020). "In addition, interdiction of pyroptosis through caspase-1/-11 or gasdermin D gene deficiency induces mice resistant to endotoxin-induced sepsis." (PMID 33002070, 2020). "The antioxidant defense enzyme glutathione peroxidase 4 (GPX4) is a negative regulator of the pyroptotic cell death pathway, and plays an important role in inhibiting lethal inflammation associated with sepsis, which suggests that lipid peroxidation can drive GSDMD-mediated pyroptosis." (PMID 32182796, 2020). "The results of this study suggested that endothelial GSDMD-mediated endothelial pyroptosis causes systemic vascular injury, which may trigger systemic hypoperfusion and organ dysfunction, ultimately leading to death in endotoxemia or sepsis." (PMID 39927458, 2025). "Thus, GSDMD has gained a lot of attraction as a potential therapeutic target for the treatment of pyroptosis‐associated diseases, including LPS‐induced endotoxemia and sepsis." (PMID 37090118, 2023). "This study demonstrates that emestrin‐type ETPs suppress GSDMD‐mediated pyroptosis through caspase‐3/7 activation, thereby attenuating inflammatory responses and conferring protection against sepsis." (PMID 41536519, 2026). "Collectively, these findings establish the therapeutic potential of targeting GSDMD‐driven pyroptosis with ETPs in sepsis and suggest their promise for clinical translation." (PMID 41536519, 2026). "Targeting GSDMD‐mediated pyroptosis therefore represents a promising therapeutic strategy for severe sepsis." (PMID 41536519, 2026). "These alterations suggest that GSDMD regulates energy, amino acid, lipid, and redox metabolism during sepsis." (PMID 41737414, 2026).
Sepsis (continued). "The occurrence of pyroptosis in the sepsis model was also reflected in the significantly enhanced GSDMD‐positive cell staining in mouse liver tissues." (PMID 40856013, 2025). "pIgR-neutralizing antibody (pIgR_Ab) exhibited opposite effects on animal survival in both sepsis models and on the injury score, caspase-11 and GSDMD-NT." (PMID 40642082, 2025). "Emerging preclinical evidence from murine sepsis models reveals that Gasdermin D (GSDMD) generates its N-terminal domain (N-GSDMD), which facilitates NET release through plasma membrane pore formation." (PMID 40766307, 2025). "Activated caspase-1 cleaves GSDMD into GSDMD-NT, which forms pores in plasma membrane, ultimately contributing to cell pyroptosis during sepsis development." (PMID 40461967, 2025). "A recent study revealed that proteins linked to the pyroptosis pathway were markedly elevated in patients with acute liver injury during sepsis, while mice with reduced expression of GSDMD exhibited less liver damage and significantly improved survival." (PMID 40458798, 2025). "In summary, ECG exerts an ameliorative effect on sepsis-induced ALI by inhibiting the NLRP3/Caspase-1/GSDMD signaling pathway." (PMID 41496909, 2025). "We further explored the role of hepatocyte‐specific replenishment of GSDMD in LPS‐induced sepsis in GSDMDhep‐/− mice." (PMID 40856013, 2025). "It suggests GSDMD as a promising therapeutic target for interrupting the mitochondrial damage and inflammatory cascade driven by pyroptosis in sepsis-related ALI." (PMID 40918090, 2025). "In order to investigate the role of hepatic GSDMD in sepsis, we constructed GSDMDflox+/+ mice and generated liver‐specific knockout GSDMD mice (GSDMDhep‐/− mice) using GSDMDflox+/+ mice and Alb‐Cre mice." (PMID 40856013, 2025). "Gasdermin D (GSDMD)‐mediated pyroptosis in macrophages plays a clear role in promoting inflammation and mortality in sepsis." (PMID 40856013, 2025). "We used CS to establish a peritoneal sepsis model and further investigated the role of endothelial GSDMD in sepsis." (PMID 39927458, 2025). "The activation of the GSDMD-NETs axis is strongly associated with the development of SIC, glycocalyx injury, and adverse clinical outcomes in sepsis, potentially contributing to these pathological processes." (PMID 40766307, 2025). "Compared with the vehicle, the GSDMD activation inhibitor significantly inhibited pulmonary edema, pulmonary microvascular permeability, and aortic permeability in mice with sepsis." (PMID 39927458, 2025). "Targeting endothelial GSDMD protected against systemic vascular injury and lethality in endotoxemia and sepsis." (PMID 39927458, 2025). "While their study focused on LPS-induced BBB disruption during sepsis, our work extends this mechanism to actual bacterial infection, showing that meningitic E. coli can trigger GSDMD-dependent pyroptosis in brain endothelial cells." (PMID 40821830, 2025). "NU6300 blocks GSDMD palmitoylation and activation by binding to the palmitoylation site of GSDMD, thereby exerting a therapeutic effect on sepsis." (PMID 40959086, 2025). "To further verify the role of GSDMD's pore‐forming activity in sepsis, we constructed full‐length GSDMD and point mutant GSDMD (c.D276A) plasmids and packaged them using adeno‐associated virus (AAV)." (PMID 40856013, 2025). "Here, we used a GSDMD inhibitor to prevent endothelial injury, systemic vascular injury, and lethality in mice with endotoxemia and sepsis successfully." (PMID 39927458, 2025). "Therapeutically, pharmacological elevation of O-GlcNAc, for example via OGA inhibitors such as Thiamet-G (TMG), suppresses GSDMD cleavage and mitigates LPS-induced pyroptosis in sepsis." (PMID 41280891, 2025). "Recent studies reveal that during acute inflammation or infection, calprotectin released from neutrophils enhances pyroptosis via the TLR4/NLRP3/caspase-1/GSDMD pathway, contributing to platelet death in sepsis." (PMID 40710328, 2025).